IL6 (interleukin 6)
Diseases named in the same sentence as IL6 in open-access papers (continued):
Sharing a sentence is not in itself a finding about the gene and the disease.
infection (continued). "Among the selected interleukin genes, IL-6, which functions in acute inflammation and B-cell maturation, was highly up-regulated (40-fold change upon infection with wild-type Cal [NS1_low-PAX_high] virus)." (PMID 30496325, 2018). "At the same time, children who later developed a secondary acquired infection had higher plasma cytokine concentrations (i.e., IL-6, IL-8, and TNF-α)." (PMID 29536210, 2018). "During infection, inflammation can induce hepcidin through the interleukin 6 (IL6)/ signal transducer and activator of transcription 3 (STAT3) pathway." (PMID 29324800, 2018). "We also demonstrated that treating mice with GalXM prior to infection with C. neoformans protects from infection, and this phenomenon is dependent on IL-6 and IL-17." (PMID 30401972, 2018). "Following infection with Campylobacter, the immune response in the cecal tissues appears to be more focused on the Th17 pathway featuring IL-6 induction with IL-17A and IL-17F responses, as compared to that observed in the ileum tissues." (PMID 29753324, 2018). "In contrast, serum IL-6 concentrations increased during sJIA flare-up and with the complication of infection; serum IL-18 concentrations increased before clinical disease activity." (PMID 29622022, 2018). "Several reports suggest that CpG-DNA pre-treatment within 72 h before infection induces cytokine expression, including IL-6, IL-12, IFN-γ, and TNF-α, which contribute to host defense." (PMID 30390012, 2018). "WT MHV-68 and MHV68/IL6 infection induced a considerably more complex proteome than DMEM-inoculated control mice." (PMID 30486363, 2018). "EHDV-TAU infection was strongly restricted by either IL-6 or IFNα, as evident by the strong reduction in both NS3 expression and production of infectious virions." (PMID 29441069, 2018). "While we did not observe significant differences in expression of IFNγ, TNF or IL-6, as compared to macrophages isolated after primary Lm-gp61 infection, heterologous challenge resulted in a significant induction in IL-12p35 expression by splenic macrophages." (PMID 29438281, 2018). "The expression level of NF-κB responsive gene Il6 was increased in Sirt6-knockdown cells after SeV (agonist of the RLR signaling) infection." (PMID 29686974, 2018). "The experimental rats’ serum stimulated a pro-inflammatory response induced by infection of P. gingivalis, while the treatment with IgY decreased the levels of IL-6 and TNF-α and shifted the immune response towards an anti-inflammatory response." (PMID 30374625, 2018). "At 24 h post-infection, the level of IL-6 mRNA in MDMs treated with antagomir-HA-3p was only 60% of that detected in cells treated with the control antagomir." (PMID 29327729, 2018). "Compared to expression levels in uninfected quarters, E. coli 1303 infection significantly induced IL-1beta, IL-6, and IL-8 concomitantly with CHI3L1 in these infected quarters." (PMID 29892291, 2018). "In infected macrophages, EV Y decreased production of PGE2 and cytokines TNF-α and IL-6 24 h after infection." (PMID 29755471, 2018). "IL-6 is one kind of the interleukin, which is a cytokine that has been verified to be highly expressed in numerous infection models." (PMID 30186539, 2018). "At 48 hours after infection, IL-6 and TNF-α were significantly increased in three groups of mice compared to sham groups." (PMID 30337682, 2018). "Interleukin-6 is a pleiotropic cytokine that plays key roles in infection and immunity via the regulation of the acute-phase response, the expansion and activation of T cells, and the differentiation of B cells." (PMID 29441069, 2018). "In contrast, the expression level of IL-6 in serum was low at 1 dpi, but increased steadily during infection and peaked at 5 dpi with a concentration of >500 pg/mL." (PMID 29511145, 2018).
infection (continued). "Infection of LNCaP-JAK1 cells in the presence of IL-6 (5 ng/mL), however, resulted in near complete abrogation of NS3 expression, suggesting a strong antiviral effect of this cytokine in JAK1-expressing cells." (PMID 29441069, 2018). "Our results showed that TLR3 knockdown in BMMs significantly impaired the expression of IFN-β and IL-6 cytokine genes upon EV-A71 infection." (PMID 30563052, 2018). "qPCR analysis indicated that transcription of downstream genes including Ifnb1, Cxcl10, and Il6 following infection with HSV-1 and VACV was markedly inhibited in Zcchc3−/− mouse bone marrow-derived macrophages (BMDMs) and dendrite cells (BMDCs)." (PMID 30135424, 2018). "The increased mRNA expression of IL-6 on SD 8 and 15 indicates an acute-phase response to infection with C. suis." (PMID 29973271, 2018). "The concentration of CHI3L1 was determined together with key infection or inflammation parameters at the local level (bacterial load, neutrophil influx, interleukin (IL)-8 and IL1beta, IL-6, RANTES/CCL5 levels)." (PMID 29892291, 2018). "Our result support this observation because il6, il1ß, il12, tnf-, ifny mRNAs are significantly induced during infection, supporting the potential development of a specific leukocyte response." (PMID 29922300, 2018). "Studies in the Democratic Republic of Congo (DRC), Cameroon, Cote D’Ivoire, Guinea and Uganda have found evidence for polymorphisms in HP, IL6 and APOL1 associated with outcome of infection." (PMID 29470556, 2018). "It has been reported that IL-6 increases in the blood after infection as an inflammatory response to regulate neutrophil and monocyte transition during the inflammation process." (PMID 30050645, 2018). "Murine colonic epithelial cells also produce high levels of IL-6 following infection with Citrobacter rodentium." (PMID 30356663, 2018). "In vitro replication of T. gondii is enhanced significantly when murine macrophages are pre-treated with IL-6 prior to infection." (PMID 30081942, 2018). "EV71 infection induces high levels of inflammatory cytokines in host cells such as IL-6, IL-10 and TNF-α, with a cytokine storm recognized as the main cause of severe cardiopulmonary manifestations during this infection." (PMID 30545363, 2018). "Administration of an IL-6-neutralizing Ab or IL-6R-blocking Ab 20 days after infection reduces Bcl6 expression, TFH and GC B cells." (PMID 30405612, 2018). "With E. histolytica, the macrophage polarization skewed towards the M1 phenotype, as shown by the significant increase in iNOS expression and multiple proinflammatory cytokines, such as TNF-α, IL-1 and IL-6, exerting immunoregulatory roles during infection." (PMID 29420539, 2018). "Il1b, Nos2 (coding for iNOS) and Il6 were upregulated in infection, however, there was similar upregulation in both mouse strains." (PMID 30169526, 2018). "The pleiotropic glycoprotein IL-6 is an important signaling molecule in the activation of the immune system in response to infections and systemic inflammation." (PMID 30591653, 2018). "In the liver on day 7 post-infection, the expression of iNOS, IL-1β, IL-6, IL-12 p40, TNF-α, IL-10, TGF-β, CCR2, CCL2, IFN-γ and IL-4 was significantly up-regulated, and the expression of Arg-1 was down-regulated in both of MRP14-KO mice and WT mice." (PMID 29902248, 2018). "4(b)) and 2(h) post infection displayed significantly increased levels of IL-1α, IL-1β, IL-6, and IL-8 when compared with the uninfected, time-matched control." (PMID 30101649, 2018). "In our study, we only found significant difference of TNF-α response in the 2000 CFU level of infection between the two strains, same as other cytokines including IL-4, IL-10, GM-CSF, IL-1β, IL-2, IL-6, IL-13, and IL-18." (PMID 30577452, 2018). "Most of the pro-inflammatory markers, such as IL-1β and IL-6, were only detected at low concentrations in the different infection groups." (PMID 30619332, 2018).
infection (continued). "We also further assessed the mRNA expression levels of the Tnf and Il6 genes at 48 hours after the infection of T. gondii in a MOI-dependent manner." (PMID 30452471, 2018). "In our previous study, the expression and secretion of IL-1β and IL-6, the major Th17-polarizing cytokines, increased in DCs upon infection with the WT strain." (PMID 30283443, 2018). "Elevated levels of IFN-β as well as the proinflammatory cytokines IL-6 and IL-8 were also observed during infection of TRIM28 KO cells with KAN-1." (PMID 30323812, 2018). "Inhibition of Notch signaling by γ-secretase inhibitor DAPT impairs TLR4-stimulated accumulation of NF-κB subunits p65 in the nucleus and subsequently reduces LPS- and infection-mediated IL-6 production." (PMID 30042932, 2018). "In the presence of CHX, IL-6 secretion was increased upon irradiation (106.24% ± 5.86%), infection (154.20%, ± 18.28%) or the combination of both (140.70% ± 22.14%)." (PMID 30524392, 2018). "The indicating biomarkers specific to chronic wounds include blood pressure, temperature, oxygen, pH, lactate, glucose, interleukin-6 (IL-6), and infection status." (PMID 29755977, 2018). "The content of IL-6 in the culture medium was increased by EV71 infection compared to mock infection (P < 0.001), while caspase-3 inhibitor reversed the increase (P < 0.001)." (PMID 29755438, 2018). "IL6 is an acute phase cytokine usually secreted during infections or tissue damage and its production is rapidly switched off after healing, but an aberrant production has been associated with several aspects of cancer biology." (PMID 29642948, 2018). "Intracytoplasmic IL-6 production was demonstrated to be nearly 4 times higher at a multiplicity of infection value of 10:1 (colony forming unit: white blood cell) than at 1:1." (PMID 29405832, 2018). "The authors noted that 1α,25(OH)2D treatment prior to or post-infection downregulated IL-6 and IL-8 RNA levels and decreased the levels of infection-induced TNFα, IFNβ, and ISG15." (PMID 30115864, 2018). "Increased serum and local levels of IL-6 were reported in humans, mammals and birds after infections with coccidia." (PMID 29973271, 2018). "In contrast, only low expression levels of TNF-α and IL-6 were detected in the microglial cells 6 and 12 hours following infection with ZIKV." (PMID 30359409, 2018). "As such, serum IL-6 levels were shown to be highly valuable in the diagnosis of infection and the prognosis of critically ill ICU patients." (PMID 30214381, 2018). "The production of IL-6 and TNFα is essential in mediating the innate immune response to infection, as well as regulating other important homeostatic processes such as wound healing and sleep." (PMID 30214381, 2018). "The protective immunity against the TB pathogen is said to be mediated by cytokines such as IFN-γ, TNF-α, IL-12, IL-6 and IL-18 during the initial stage of infection." (PMID 30583589, 2018). "CXCL8 is a chemokine that recruits neutrophils to the site of infection, whereas IL‐6 is an important proinflammatory cytokine and an important mediator in acute inflammation." (PMID 29536668, 2018). "Infection of placental cells induced lesser amounts of these mediators with significantly higher secretion of IL-6 and sICAM-1 in HEV-1 infected cultures." (PMID 30420629, 2018). "The Th1 responses and regulation of the recruitment of Th1 immune cells to the site of infection are characterized by expression of key cytokines and chemokine such as TNFα, IL-12, IFNγ, IL-6, IL-10 and MCP-1 among others." (PMID 30413750, 2018). "IL-6 is secreted by a variety of cell types and plays a role in inflammation, response to infection, and wound repair in vivo." (PMID 29707119, 2018). "One of the principal cytokines, interleukin-6 (IL-6), is involved in inflammation and infection responses as well as in the regulation of metabolic, regenerative, and neural processes." (PMID 29438401, 2018).
infection (continued). "Analyzing the inflammatory response in the lungs, we saw, as expected, an induction of pro- (IL-1β, TNF-α, KC, IL-6) and anti-inflammatory (IL-10) chemo- and cytokines following infection with S. pneumoniae." (PMID 29449834, 2018). "Studies to investigate the role of specific cytokines and chemokines in the response to infection have shown that these mediators can be beneficial (e.g., IL-6, TNF-α, IL-1, and CXCR1) (62, –, 65), or they can be detrimental (CCR1)." (PMID 29666281, 2018). "Since IL-6 can be produced by various hematopoietic and non-hematopoietic cells, we suggest that APCs are relevant cellular sources of IL-6 for the differentiation of IL-17 secreting cells during infection." (PMID 29338039, 2018). "IL-6 increased by 6-fold at 7 days post-infection and remained around 70 ± 10 pg/ml throughout the infection." (PMID 29896527, 2018). "Infection of BMDMs cells with Hh induced a sustained release of the pro-inflammatory cytokines IL-6 and TNFα in the supernatants as compared to unstimulated BMDM." (PMID 29636751, 2018). "Indeed, infection caused upregulation of IL-6, TNFα and IL-1β, typically associated with classical activation, as well as of arginase and IL-10, which is linked to regulatory macrophages and may have profound suppressive effects on both innate and adaptive responses." (PMID 29579113, 2018). "Its overexpression in macrophages has been linked to a significant decrease in MyD88 protein expression, as well as a reduced production of inflammatory mediators such as NF-κB, TNF-α, and IL-6 in response to infection or LPS stimulation." (PMID 29988529, 2018). "Differences in biomarkers (higher Hp and IgG1; lower SAA and IL-6) between perinatal mortalities and live perinates probably reflect differences between these two groups in age at sampling (SAA and IL-6) and in utero infection (IgG1)." (PMID 30382887, 2018). "Meanwhile, TSA treatment pre-infection induced a significant decrease of IL-6 production at all concentration tested ranging from 69% to 89.6% compared with infected non-treated control cells." (PMID 29986388, 2018). "TNF and IFNγ had opposite effects on IL-6 production, with IFNγ neutralization resulting in a significant increase in IL-6, with concentrations similar to that of a primary Lm-gp61 infection." (PMID 29438281, 2018). "A continuous increase of IL-6 secretion during infection mediates host defense and cell survival in different bacterial infections." (PMID 29500439, 2018). "A similar course of infection, proinflammatory mediator profile, neutrophil infiltration, and architectural changes to the retinal layers were observed in both IL-6−/− and C57BL/6 J eyes." (PMID 29661181, 2018). "Kingsley and Jones stated that CRP increases during infection in response to monocytic mediators such as IL-1 and IL-6 and that it has a stable decay rate." (PMID 29706967, 2018). "IL-6 then appeared, presumably to sustain the inflammatory response at the middle infection stage, and possibly also to transmit/represent a warning signal in the event of tissue damage." (PMID 30037796, 2018). "At the molecular level, we found IL-6 and IL-1 to act synergistically and complementary to IL-23 for instruction of IL-17 in response to infection." (PMID 29782555, 2018). "Previous studies have shown that H. pylori stimulates secretion of the proinflammatory cytokines IL-8 and IL-6 upon infection of endothelial cells." (PMID 29468142, 2018). "In the case of resting cells stimulated by LEC-, the addition of anti-IL-6 antibody nearly reduced the infection rates to the level of unstimulated resting cells, suggesting that IL-6 was almost solely responsible for the effect of LEC- stimulation." (PMID 30285810, 2018). "In agreement with El-Deeb and Elmoslemany, proinflammatory cytokines' serum levels (TNF-α and IL-6) were markedly elevated to enhance leukocyte migration into the infection site." (PMID 30050645, 2018).
infection (continued). "We observed a trend towards increased levels of TNFα, IL-6, IL-1β, and IL-1α in the lung tissue of p110δE1020K-GL mice at 24 h post-infection." (PMID 30093657, 2018). "Next, we addressed the induction of ISGs by EHDV-TAU infection in the absence or presence of IL-6 or IFNα." (PMID 29441069, 2018). "We also assessed the mRNA expression levels of the Tnf and Il6 genes at 18 hours after the infection of Mab in a MOI-dependent manner." (PMID 30452471, 2018). "All untreated animals had a cytokine storm characterized by a continuous increase in cytokines levels, in particular pro inflammatory IL6, TNFα, IFNα, from day 5 post infection (D5) to the time to death." (PMID 30275474, 2018). "An infection with L. major or L. donovani with subsequent activation with LPS resulted in a strong IL-6 expression." (PMID 29403488, 2018). "Together, these findings demonstrate a key role for IL-6 during infection and further supports the anti-viral role of neutrophils in aiding IAV clearance and disease resolution." (PMID 30254192, 2018). "Nonetheless, in white blood cells, IL-4, IL-6 and IL-10 mRNA-levels significantly increased after infection, whereas IFN-ɣ, IL-2 and TGF-β expression tended to decrease." (PMID 29973271, 2018). "Infection with the LPS-deficient strain resulted in lower serum levels of pro-inflammatory cytokines TNF-α and IL-6 compared to the parent strain, and was less virulent in a mouse model of disseminated sepsis." (PMID 29638177, 2018). "Infection of IL-6 silenced cells resulted in chlamydial infectivity of 100.48% (±38.81%; p-value > 0.05) of the control." (PMID 30524392, 2018). "Subjects with Staph, Cor/All, Mor, and Ps/Mix clusters were found to have differences in CCL2, CCL20, IL-6, and G-CSF responses during the infection." (PMID 30061588, 2018). "The serum cytokines such as IFN-β, CXCL10, and IL-6 induced by infection of HSV-1, VACV, and MCMV were impaired in Zcchc3−/− in comparison to Zcchc3+/+ mice, and ZCCHC3-deficiency renders the mice more susceptible to HSV-1- or VACV-induced death." (PMID 30135424, 2018). "High production of Th2 inflammatory mediators such as interleukin 6 (IL-6) was reported in T. gondii and E. tenella mono-infections." (PMID 30081942, 2018). "In the present study, we observed lower concentrations of Th1 cytokines (IFN-γ, TNF-α, IL-6) on day 3 post-infection) and lower concentrations of one Th2 cytokine (IL-10) in infections of BCG+ donor PBMCs compared to BCG- donor PBMCs." (PMID 30204787, 2018). "Other pro-inflammatory responses that were also elevated in the presence of properdin at initial stages of infection are IL-1β and IL-6." (PMID 29867915, 2018). "In turn, IL6 affects the production of histamine by human MCs in vitro and other regulatory molecules involved in the control of infection." (PMID 30012189, 2018). "Markers of inflammation, including neutrophil infiltration and proinflammatory cytokine production in the BALF, such as TNF-α, IL-1β and IL-6, were determined 24 h post-infection." (PMID 29875759, 2018). "There is a report that MRP14 induces the secretion of TNFα, IL-1β and IL-6 dependent on TLR4, and it is also reported that these inflammatory cytokines can be associated with the pathology during infection with P. berghei." (PMID 29902248, 2018). "The DEGs involved in cytokine signaling were also up-regulated following infection with EV-F7, and included IL-6, IL-11, leukemia inhibitory factor (LIF), granulocyte-macrophage colony-stimulating (GM-CSF), and colony stimulating factor 2 (CSF2)." (PMID 30545363, 2018). "While the secretion of proinflammatory cytokines IL-6 and TNFα was similar in both infections, the output of regulatory IL-10 was significantly higher in wild type infection, indicating that the M5 protein promotes secretion of IL-10." (PMID 29579113, 2018).